INS (insulin)
Diseases named in the same sentence as INS in open-access papers (continued):
Sharing a sentence is not in itself a finding about the gene and the disease.
type 2 diabetes (continued). "This secondary analysis of a randomized clinical trial examines associations of growth hormone mediators with glycemic failure, beta cell function, and insulin sensitivity in youth-onset type 2 diabetes." (PMID 38421647, 2024). "To test the therapeutic potential of the Crotalus venom peptide-rich fraction to treat type-2 diabetes and obesity, we used in vitro models to test insulin resistance and adipocyte lipid accumulation." (PMID 39398348, 2024). "Exposure to roxadustat reduced insulin-stimulated phosphorylation of Akt-Ser473 in myotubes from donors with type 2 diabetes and insulin-stimulated phosphorylation of GSK3β-Ser9 in myotubes from both groups." (PMID 38814443, 2024). "Acute counterregulatory hormone and symptom responses to experimental hypoglycaemia are lower in people with type 1 diabetes than in those with long-standing insulin-treated type 2 diabetes and controls." (PMID 38376580, 2024). "The primary defects in type 2 diabetics are the dysfunction of beta-islet cells and impaired insulin secretion in response to glucose stimulation, which involve a series of ion-channel activities." (PMID 39568816, 2024). "One of these miRNAs, miR-107, regulates insulin sensitivity and is postulated as a target for the treatment of type 2 diabetes and obesity." (PMID 37106037, 2024). "We present a case of a 68-year-old male with type 2 diabetes, who was on insulin lispro protamine and underwent elective CABG." (PMID 39421103, 2024). "An RCT in 136 individuals with type 2 diabetes showed that, compared with subcutaneous insulin therapy, a fully AID system resulted in a significant 24.3 pp TIR increase and 25.9 pp TAR reduction without increasing hypoglycaemia." (PMID 38951212, 2024). "GLP-1 secretion is reduced in type 2 diabetes patients after an oral glucose load and during a meal test, whereas stimulation of insulin secretion by GLP-1 infusion is relatively well preserved in diabetic patients." (PMID 39458507, 2024). "Type 1 diabetes (T1D) is when beta cells in the pancreas stop producing insulin, while Type 2 diabetes (T2D), previously referred to as adult-onset diabetes, occurs when muscle, liver, and fat cells develop resistance to insulin." (PMID 38811939, 2024). "The pathogenesis of type II diabetes centers on insufficient insulin production by pancreatic β cells." (PMID 39796443, 2024). "Type 2 diabetes is reaching pandemic proportions, and is characterized by impaired insulin sensitivity." (PMID 38921470, 2024). "Treatment of type 2 diabetic rats with high doses of disulfiram also reverses diabetes progression by restoring insulin homeostasis." (PMID 39133222, 2024). "All participants with type 2 diabetes had preserved endogenous insulin secretion with C-peptide levels of 1.35 [0.47–2.99] nmol/L." (PMID 38376580, 2024). "People with type 2 diabetes are heterogeneous in their disease trajectory, with some progressing more quickly to insulin initiation than others." (PMID 38374450, 2024). "Type 2 diabetes was present in 24% (n = 112) of patients, which was treated with the following strategies: sulfonylureas 25%, metformin 54%, insulin 18%, and thiazolidinediones 5%." (PMID 38623877, 2024). "The deterioration of β-cell function and the concomitant damaged insulin secretion results in chronic hyperglycemia, which characterizes type 2 diabetes, currently affecting about 422 million people worldwide." (PMID 39056663, 2024). "Similar variations were observed in type 2 diabetes with insulin costs of around US$ 50 –US$ 100 for each patient annually." (PMID 39361609, 2024). "Metformin is an insulin-sensitizing drug used as first-line therapy in the management of type 2 diabetes (T2D)." (PMID 38367137, 2024). "In conclusion, our study is the first to demonstrate that insulin secretory capacity is associated with TIR in Japanese patients with type 2 diabetes, showing that TIR increases with preserved insulin secretory capacity." (PMID 38839813, 2024).
type 2 diabetes (continued). "An RCT involving 72 insulin-treated participants with type 2 diabetes did report a reduction in hypoglycaemic events (<3.9 mmol/l) in hospital during CGM use compared with POC-BG monitoring (0.67 vs 1.69 events/participant, p=0.024)." (PMID 38953925, 2024). "Insulin glargine U100 (Gla-100) is a long-acting insulin widely used in both type 1 and type 2 diabetes." (PMID 38541176, 2024). "The related studies in clusters 0 (foot ulcer), 1 (insulin secretion), and 2 (diabetic retinopathy) spanned from 2013 to 2023 and focused on keywords such as pathogenesis, type 2 diabetes, injury, cancer, angiogenesis, and activation." (PMID 39195499, 2024). "Ten participants were treated for Type 2 diabetes prior to surgery (3 with insulin and 7 with oral hypoglycaemic agents), 18 were treated for hypertension, and 9 were treated for dyslipidemia." (PMID 39403074, 2024). "It has been suggested that the postprandial ICR profile in those with type 2 diabetes is due to the reduced hepatic delivery of insulin (i.e. beta cell dysfunction), rather than an impairment in the liver to adjust the clearance of insulin." (PMID 39138690, 2024). "Formerly referred to as non-insulin-dependent, type 2 or adult-onset diabetes, type 2 diabetes is its current." (PMID 38725826, 2024). "As severe beta-cell dysfunction leads to a worsening short-to-intermediate GV, patients with insulin-dependent type 1 diabetes have high day-to-day GV and experience more frequent hypoglycemic events compared with insulin-independent type 2 diabetes." (PMID 38541176, 2024). "Type 2 diabetes mellitus is a chronic disease characterized by insulin resistance and inadequate pancreatic insulin secretion, resulting in hyperglycemia, and requiring continuous medical care." (PMID 38627464, 2024). "Even though the substitutions in insulin icodec significantly stabilise insulin against such degradation, some free B-chain is observed in plasma samples from minipigs and people with type 2 diabetes." (PMID 39033137, 2024). "Equal amounts of energy were compared in 10 patients with type 2 diabetes, and milk and lactose-based meals led to a similar glucose response, but there was a lower insulin response in milk than with the lactose meal." (PMID 39056692, 2024). "Type 2 diabetes mellitus (T2DM) is a group of metabolic disorders characterized by high serum glucose levels due to insufficient insulin supply, defective receptor function, or both." (PMID 38907052, 2024). "The present study aimed to compare the cost-effectiveness of a CGM device (FreeStyle Libre 2) with a CBG device for managing glycemic control in inpatients with type 2 diabetes undergoing intensive insulin therapy." (PMID 38476508, 2024). "This explains the fact that circulating insulin levels are often higher in the early phases of type 2 diabetes." (PMID 39768947, 2024). "The treatment of type 2 diabetic KK-Ay mice (an experimental model of T2DM) with an AT1R antagonist (valsartan) significantly improved insulin sensitivity and reduced the plasma glucose level." (PMID 38279313, 2024). "When comparing our findings to a study investigating the relationship between insulin treatment and the risk of major adverse cardiovascular events (MACE) in stable type 2 diabetes patients, especially those with recent acute coronary syndrome (ACS)." (PMID 39295783, 2024). "In contrast, the studies that included only subjects with type 1 diabetes receiving insulin therapy or individuals with both type 1 and type 2 diabetes showed an increased time in hyperglycemia and glucose variability during RF." (PMID 39203800, 2024). "Compared with all cell types, beta cells had the most genes with time–glucose interaction effects, featuring several well-established type 2 diabetes genes, including INS, ABCC8, SLC30A8 and PCBD1." (PMID 38967666, 2024).
type 2 diabetes (continued). "The insulin abnormalities induced by IR are particularly pronounced in obese individuals and those with type 2 diabetes, leading to an excessive activation of the sympathetic nervous system." (PMID 38278849, 2024). "Type 2 diabetes is recognized a “redox disease” and the various roles of oxidants in regulating insulin signaling are currently well recognized." (PMID 38519940, 2024). "The results from this study showed that the proportion with insulin treatment increased significantly faster over time among individuals with cancer and type 2 diabetes compared with type 2 diabetes controls." (PMID 39020360, 2024). "Metformin, a widely used first-line anti-diabetic therapy for the treatment of type-2 diabetes, has been shown to lower hyperglycemia levels in the blood by enhancing insulin actions." (PMID 38791227, 2024). "The pathogenesis of cognitive dysfunction due to type 2 diabetes includes tau phosphorylation due to increased insulin resistance, neuronal and synaptic damage via amyloid-β accumulation, and vascular damage." (PMID 38854809, 2024). "A double randomised, double-blinded, placebo-controlled clinical trial was run for 2 years in Australia on type 2 diabetes people to determine the effect of third stage N. americanus larvae infection on the insulin resistance." (PMID 39204303, 2024). "We present evidence that IGFBP7 is a negative regulator of insulin secretion and is upregulated in type 2 diabetes." (PMID 39280605, 2024). "The SCFAs, mainly butyrate, acetate, and propionate, can affect human health including potential benefits for insulin sensitivity and management of type 2 diabetes and obesity." (PMID 38753173, 2024). "This reduction has been shown to significantly enhance insulin sensitivity and glycemic control and positively impact hypertension and lipid profiles in individuals with type 2 diabetes." (PMID 38750304, 2024). "Circulating sonic hedgehog- (Shh-) positive exosomes were increased in type 2 diabetes patients, and high glucose and insulin increased the secretion of Shh-positive adipocyte-derived exosomes (ADEs)." (PMID 38455849, 2024). "Individuals with type 1 and long-standing type 2 diabetes require insulin to regulate blood glucose levels, which is essential for their survival." (PMID 38675446, 2024). "In individuals with type 2 diabetes, the insulin and C-peptide responses to an oral glucose load were found to be notably elevated in smokers compared to non-smokers." (PMID 39478763, 2024). "Insulin doses requirements in pregnancy were relatively in line with doses observed in women with type 2 diabetes." (PMID 38461278, 2024). "Insulin is a critical treatment for patients with type 1 diabetes and those with type 2 diabetes who require insulin." (PMID 39457586, 2024). "The liver plays a vital role in controlling the circulating lipid and glucose levels, and the development of type 2 diabetes and atherosclerosis due to dysregulated hepatic fat content, insulin sensitivity, and glucose production." (PMID 39113703, 2024). "Current treatments for type 2 diabetes (T2D) mainly rely on exercise, dietary control, and anti‐diabetic drugs to enhance insulin secretion and improve insulin sensitivity." (PMID 39113101, 2024). "As insulin is required for the synthesis and storage of triacylglycerol in fat cells, there is a depletion of body fat stores in type 2 diabetes." (PMID 38707092, 2024). "In response to the glucagon infusion, the control group exhibited a larger increment in insulin levels compared to the type 2 diabetes group." (PMID 38276866, 2024). "GLP-1 peptide increases and decreases insulin and glucagon secretion, respectively, and modulates blood glucose levels and also one of the therapeutic targets for type 2 diabetes mellitus are GLP-1RAs (GLP-1 receptor agonists)." (PMID 38807723, 2024).
type 2 diabetes (continued). "Type 2 diabetes (T2D) is a common metabolic disorder characterized by high blood glucose levels, due to low insulin or insulin resistance and affects more than 500 million people worldwide." (PMID 39464637, 2024). "Altogether, these findings indicate that bariatric surgery results in an immediate beta-cell function recovery in insulin-treated type 2 diabetes." (PMID 38589596, 2024). "Patients with type 2 diabetes have an impaired insulin response to GLP-1 that is believed to be secondary to reduced post-prandial GLP-1 secretion." (PMID 38730578, 2024). "Type 2 diabetes mellitus (T2DM) is a complex endocrine and metabolic disorder, which is characterized by deficient insulin secretion, insulin resistance (IR), and/or pancreatic islet β-cell failure to maintain normoglycemia." (PMID 39000039, 2024). "During the pathogenesis of type 2 diabetes, beta cells often hyper-secrete insulin to compensate for declining tissue sensitivity to insulin and this is associated with increased production of ROS." (PMID 38479223, 2024). "As part of this initiative, a single database was created based on insulin clinical trial data provided by several pharmaceutical industry partners from people with type 1 or type 2 diabetes in whom hypoglycaemia events occurred for the duration of the trials." (PMID 39037602, 2024). "A subsequent meta-analysis demonstrated that the administration of vitamin D supplements resulted in improved glycemic measures and enhanced insulin sensitivity, thereby potentially serving as a preventive measure against the development of type 2 diabetes." (PMID 38216955, 2024). "MASLD and MASH are highly associated (50%–80%) with other metabolic comorbidities such as impaired insulin response, type 2 diabetes, dyslipidemia, hypertriglyceridemia, and hypertension." (PMID 39086662, 2024). "This, in turn, can lead to the inhibition of insulin activity and secretion, accelerating the onset of type 2 diabetes." (PMID 38921462, 2024). "Chronic hyperglycemia in Type 2 Diabetes (T2D) has been recognized to lead to insulin insensitivity by damaging pancreatic β-cells." (PMID 39562539, 2024). "Another study found that a higher risk of type 2 diabetes is associated with the hypermethylation of the PPARG promoter in the pancreatic islets of diabetic patients, which negatively correlated with insulin secretion." (PMID 39595621, 2024). "Disability due to obesity-induced type 2 diabetes would also increase, particularly in low- and middle-income countries, asthe supply of insulin in these countries is comparatively insufficient." (PMID 40230911, 2024). "In agreement with an insulin secretion defect, the Atm−/− mice developed fatty livers, a condition characteristic of type 2 diabetes and reported in A-T patients." (PMID 39281865, 2024). "Switching metabolism to improve cardiovascular outcome in type 2 diabetes has been tried before by increasing cardiac glucose utilization with insulin." (PMID 38184612, 2024). "In Western populations, the incretin effect is reduced in type 2 diabetes, leading to lowered insulin secretion." (PMID 39049087, 2024). "He had a history of hypertension, type 2 diabetes on insulin, obesity, coronary artery disease with HFpEF, and mild diastolic dysfunction (on double diuretic therapy)." (PMID 38330042, 2024). "We aim to enrich the field by reporting the case of our patient with type 2 diabetes on insulin therapy who had lipodystrophy with an uncommon clinical presentation." (PMID 39691127, 2024). "A study comparing preprandial vs. postprandial insulin glulisine in patients initiating a basal–bolus regimen for type 2 diabetes showed that nocturnal hypoglycemia rates were higher in the postprandial administration group." (PMID 39062173, 2024).
type 2 diabetes (continued). "The downregulation of cd302 can increase insulin secretion and promote β cell survival, which makes it an attractive target for developing new medicine to treat type II diabetes and its complications (such as diabetes nephropathy)." (PMID 39364045, 2024). "For instance, it has been shown to reduce fasting blood glucose levels, improve insulin sensitivity, and enhance peripheral microvascular perfusion, all while lowering blood pressure in animal models and patients with type 2 diabetes (T2D)." (PMID 39679375, 2024). "In type 2 diabetes, the pancreatic beta cells fail to produce sufficient insulin, and peripheral tissues become resistant to insulin." (PMID 39766863, 2024). "Thiazolidinediones—PPARγ agonists, commonly used as insulin sensitizers for type 2 diabetes—have also been studied for their ability to promote thermogenic gene expression in both white and brown adipocytes." (PMID 39519099, 2024). "PPARγ agonists are commonly used in the treatment of type 2 diabetes to increase sensitivity to insulin." (PMID 38992135, 2024). "On the other hand, the upregulated miRNAs demonstrate predictive function in regulating FoxO, Ras, TGF‐β, Pi3K‐Akt, MAPK, mTOR, insulin signaling, and type II diabetes mellitus." (PMID 38751007, 2024). "In patients with type 2 diabetes who were introduced to intensive insulin therapy using continuous subcutaneous infusion, a reduction in pro-inflammatory cytokines was observed." (PMID 39594627, 2024). "Fasting insulin and liability to type 2 diabetes had similar metabolic signatures encompassing a wide range of lipids and amino acids." (PMID 38459184, 2024). "A base-case analysis showed that long-term isCGM use was cost-effective compared with SMBG in individuals with type 2 diabetes receiving intensive insulin treatment." (PMID 38951212, 2024). "In type 2 diabetes patients, a reduction in skeletal muscle Mfn2 expression has been observed, with Mfn2 levels correlating positively with insulin sensitivity." (PMID 39763653, 2024). "Overall, both BMI and insulin change have strong effects on the models, and the effects of both glucose change and type 2 diabetes are minor." (PMID 38191968, 2024). "Firstly, we have shown that the PPARG promoter is hypermethylated in obese and type 2 diabetic patients, which correlates with the downregulation of the expression of numerous genes responsible for proper insulin signal transduction in adipocytes." (PMID 39595621, 2024). "The aim of this study was to determine the effect of administering insulin and metformin on the mortality of patients with type 2 diabetes (T2DM) with symptomatic COVID-19 with the use of logistic regression models." (PMID 38540218, 2024). "The generation of insulin-producing cells to compensate for their absolute or relative shortage in type 1 and type 2 diabetes is an obvious therapeutic strategy." (PMID 39629270, 2024). "A subsequent open-label randomised clinical trial compared different icodec titration strategies with glargine U100 in 205 insulin-naive participants with type 2 diabetes over a 16 week period." (PMID 38679644, 2024). "In low middle income countries (LMIC), individuals with type 2 diabetes are often started on insulin later in the disease progression due to clinical inertia and patient resistance." (PMID 39553731, 2024). "Changes in insulin concentrations reflect those of BMI with robust decreases from 16.5 (13.3–27.5) mU/L to 8.0 (7.0–10.8) mU/L for the type 2 diabetes group and from 16.5 (9.0–26.5) mU/L to 10.0 (7.8–14.0) mU/L for the nondiabetic group." (PMID 38191968, 2024). "In this research, we propose a machine-learning based system to predict the 2 h after meal BGL of Type 2 diabetes patient, taking the meal intake, insulin or medicine, physical exercises, etc. into account." (PMID 38617952, 2024).